RHBDD2 (rhomboid domain containing 2)
Synonyms: RHBDL7; NPD007
Tractability: Antibody: UniProt predicts a signal peptide or a membrane-spanning region. PROTAC: ubiquitination databases record sites on it; its protein half-life has been measured.
Gene: Protein-coding gene on chromosome 7 (75,842,602 to 75,888,927, forward strand). Ensembl gene ENSG00000005486.
Subcellular location: Golgi apparatus, cis-Golgi network membrane
Subcellular location (Human Protein Atlas): Golgi apparatus
Gene Ontology:
Molecular function: signal recognition particle binding; serine-type endopeptidase activity
Biological process: endoplasmic reticulum unfolded protein response; ERAD pathway
Cellular component: Golgi apparatus; endoplasmic reticulum membrane; Golgi membrane; membrane; perinuclear region of cytoplasm
Genetic constraint (gnomAD): Loss-of-function variants: 10 observed, 15.08 expected, observed/expected ratio (o/e) 0.66, 90% interval 0.41 to 1.12. The upper end of that interval is the gene's LOEUF score, 1.12, which puts it in group 4 of 6, group 1 being the genes least tolerant of losing a copy. Missense variants: 455 observed, 447.47 expected, observed/expected ratio (o/e) 1.02, 90% interval 0.94 to 1.1. Synonymous variants: 216 observed, 201.96 expected, observed/expected ratio (o/e) 1.07, 90% interval 0.96 to 1.2.
Homologues: Orthologues: chimpanzee RHBDD2 (100% identical), macaque RHBDD2 (99% identical), mouse Rhbdd2 (87% identical), rabbit RHBDD2 (87% identical), pig RHBDD2 (87% identical), rat Rhbdd2 (86% identical), dog RHBDD2 (78% identical), guinea pig RHBDD2 (74% identical), tropical clawed frog rhbdd2 (31% identical), zebrafish rhbdd2 (21% identical). Paralogues in human: RHBDD3 (17% identical), RHBDD1 (15% identical).
Diseases named in the same sentence as RHBDD2 in open-access papers:
RHBDD2 is named in the same sentence as 9 diseases in open-access papers, as found by Europe PMC text mining. Sharing a sentence is not in itself a finding about the gene and the disease. The quoted sentences say what the papers report.
breast carcinoma (2 papers, 2020 to 2023). "RHBDD2 is a member of the rhomboid family of membrane-bound proteases and is known to be overexpressed in the advanced stages of breast cancers and colorectal cancers." (PMID 37264057, 2023). "There are little or no reports on the methylation status of RHBDD2, but it was found to be overexpressed in CRC, breast cancer, and as a pathogenic gene in familial non-medullary thyroid cancer (FNMTC)." (PMID 32605309, 2020).
colorectal cancer (2 papers, 2018 to 2024). A primary or metastatic malignant neoplasm that affects the colon or rectum. "The RHBDD2 (Rhomboid domain containing 2) gene is found to be overexpressed in advanced stages of colorectal cancer (CRC) and potentially modulates the UPR pathway, thereby favoring cell migration, adhesion, and proliferation." (PMID 38167084, 2024). "RHBDD2, a member of the rhomboid family, is reported to express a significant increase in breast primary tumors with a more disseminated disease than with less disseminated tumors; overexpression in advanced stages of colorectal cancer is also observed." (PMID 29426364, 2018).
Alzheimer disease (1 paper, 2022). A progressive, neurodegenerative disease characterized by loss of function and death of nerve cells in several areas of the brain leading to loss of cognitive function such as memory and language. "In addition, synonymous variants in 4 genes [(Cadherin Related 23 (CDH23), SLC9A3 Regulator 1 (SLC9A3R1), Rhomboid Domain Containing 2 (RHBDD2), and Inter-Alpha-Trypsin Inhibitor Heavy Chain 2 (ITIH2)] linked with alzheimer's disease warrant comprehensive scrutiny of genetic variations." (PMID 36434531, 2022).
pancreatic cancer (1 paper, 2023). "In addition, the low expression of RHBDD2 in supporting cells, specifically fibroblasts, of clinical pancreatic cancer showed a shortened prognosis, and a negative correlation with CXCL12 was observed." (PMID 37264057, 2023).
cancer (3 papers, 2018 to 2024). A tumor composed of atypical neoplastic, often pleomorphic cells that invade other tissues. "These collective findings underscore the significance of RHBDD2 as a prospective therapeutic target, emphasizing its role in facilitating chemoresistance and invasiveness in cancer." (PMID 38267862, 2024). "Knocking out C9orf89, MAGI2, MLPH, or RHBDD2 in supporting cells reduced the ratio of apoptosis of cancer cells." (PMID 37264057, 2023). "Additionally, immunohistochemical staining of CXCL12 was conducted to assess the association between RHBDD2 and CXCL12 expression in fibroblasts surrounding carcinoma cells." (PMID 37264057, 2023). "RHBDD2 might play a role in cancer metastasis, while the mechanism is completely unknown." (PMID 29426364, 2018).
tumor (2 papers, 2023 to 2024). "Immunohistochemistry analysis demonstrated a decline in RHBDD2 expression in the miR-4739 mimics group, while an increase was observed in the group where miR-4739 mimics were combined with RHBDD2 in xenograft tumor tissues." (PMID 38267862, 2024). "RHBDD2-CKO-induced upregulation of CXCL12 in stromal cells leads to anticancer drug resistance via activating the PI3K-Akt-mTOR pathway in tumor cells." (PMID 37264057, 2023). "Among them, rhomboid domain containing 2 (RHBDD2) is an intramembrane pseudoprotease member of the rhomboid family that shows elevated expression levels during mammary gland development and in advanced tumor stages." (PMID 38267862, 2024). "Additionally, quantitative real-time PCR confirmed the upregulation of miR-4739 and downregulation of RHBDD2 in xenograft tumor tissues derived from the miR-4739 mimics group." (PMID 38267862, 2024). "Six parameters, including age, pT category, tumor size, UICC stage, MAGI2, and RHBDD2, were tested by multivariate analysis using the Cox proportional hazard model." (PMID 37264057, 2023). "However, these previous studies focused on the expression of RHBDD2 in the tumor cells themselves, and there are no reports examining its expression in peritumoral supporting cells." (PMID 37264057, 2023).
RHBDD2 also shares sentences with these, for which no sentence is quoted: cervical cancer (1 paper); leukemia (1); pancreatic ductal carcinoma (1).